VIM (vimentin)
Diseases named in the same sentence as VIM in open-access papers (continued):
Sharing a sentence is not in itself a finding about the gene and the disease.
tumor (continued). "Unlike the findings reported for some precursor lesions in human VHL patient kidneys, Vhl mutant cystic lesions and neoplasms in the mouse retain expression of the epithelial marker E-cadherin and do not display the mesenchymal marker vimentin." (PMID 23606570, 2013). "In our case, the tumor cells were positive for vimentin and SMA and negative for desmin and cytokeratin." (PMID 23936706, 2013). "Importantly, we observed co-expression of vimentin and acetylated histone 3 at the invasion front of human HNSCC tumor tissues." (PMID 23527004, 2013). "Both reduced E-cadherin and overexpression of Vimentin are observed during EMT and cancer progression, leading to the shedding of the cancerous cells from the primary tumour." (PMID 24092663, 2013). "Immunostaining showed that the tumor was positive for the Vimentin, Desmin and MyoD1, and was negative for CK, P63, NSE, CD45, CD30, S-100, CD99, Myoglobin, CD68, CD34, CD31, and α–SMA." (PMID 23379991, 2013). "Immunostaining showed that the tumor was strongly positive for Vimentin, Desmin and MyoD1, and was negative for CK, P63, NSE, CD45, CD30, S-100, CD99, Myoglobin, CD68, CD34, CD31, α–SMA." (PMID 23379991, 2013). "Immunohistochemically, the resected tumor stained positively for the epithelial markers, epithelial membrane antigen (EMA) and cytokeratin 19 (CK 19), and the mesenchymal markers, smooth muscle actin (SMA) and vimentin." (PMID 23426899, 2013). "Immunohistochemically, the resected tumor stained positively for epithelial markers of epithelial membrane antigen (EMA) and cytokeratin 19 (CK 19), and mesenchymal markers of smooth muscle actin (SMA) and vimentin." (PMID 23426899, 2013). "Next, to determine whether the shift toward resistance obtained in vitro could be recapitulated in a 3D tumor spheroid assay, the sensitive RKO cells containing a vimentin knockdown shRNA construct were exposed to PF-3758309 and scored in a 3D assay." (PMID 23543898, 2013). "Tumor cell morphology evidenced by vimentin staining was not altered by DMN treatment, even at the highest doses." (PMID 24327603, 2013). "On the other hand, in a case of SCC mimicking atypical fibroxanthoma expression of both SNAI1 and vimentin and absence of keratin expression were observed in tumor cells." (PMID 23984088, 2013). "The most important feature in HPC is extensive irregular staghorn vascular pattern, Immunohistochemistry tumor cells showed vimentin and actin focal positivity and were negative for CD34." (PMID 24294990, 2013). "In our case, the tumor cells were positive for vimentin, CD10, and pancytokeratin, but negative for CK7, CEA, chromogranin, synaptophysin and CD68." (PMID 23305230, 2013). "The tumor cells showed positive immunostaining for cytokeratin and vimentin suggesting epithelial origin of the tumor and negative for melanin-specific HMB-45." (PMID 23607017, 2013). "Primary Tumor Foci #1-5 stained strongly for the epithelial marker E-cadherin and displayed only scattered weak staining for CK8/18, CK5, and the mesenchymal marker vimentin (top row)." (PMID 23049838, 2012). "Isolation by size of epithelial tumour cells detected more CTCs and identified Vimentin-positive CTCs in patients who did not have detectable CTCs by CellSearch." (PMID 22187035, 2012). "Immunohistochemistry is useful because the tumor cells are positive for S-100 protein and vimentin and negative for epithelial and myoepithelial cell markers." (PMID 22844293, 2012). "A previous RCC study demonstrating AQUA used a non-cytokeratin based tumour mask, specifically a vimentin/EMA/CD10 combination." (PMID 22363672, 2012). "An immunohistological examination showed that the tumor cells were strongly positive for vimentin and S-100 (data not shown)." (PMID 23320224, 2012). "Immunohistochemically, the tumor cells were positive for vimentin, Ki-67, smooth muscle actin (SMA), and CD34, but negative for S-100." (PMID 23152982, 2012).
tumor (continued). "Immunostaining showed that the tumor was positive for the Vimentin, Bcl-2 and CD34, and was negative for S-100, desmin, CD68 and α–SMA." (PMID 23148444, 2012). "All tumor samples were negative for estrogen receptor α (ERα) and the mesenchymal marker vimentin (data not shown)." (PMID 22233382, 2012). "Immunohistochemically, the tumor cells were positive for vimentin, CD56, synaptophysin (focal) but negative for EMA, cytokeratin, S-100." (PMID 23217062, 2012). "Immunohistochemically, the tumor cells showed positive reactivity for vimentin, Ki-67, smooth muscle actin, and CD34, but negative staining for S-100." (PMID 23152982, 2012). "The viable tumor cells showed a strong membranous stains for CD99, focal membranous and cytoplasm stain for CD56, a cytoplasm dot pattern for synapthophysin, and focal cytoplasm and membranous stain for PGP9.5, BCL2, and vimentin." (PMID 22312368, 2012). "Although all the tumor samples were negative for vimentin, another mesenchymal marker fibronectin was detected in all samples." (PMID 22233382, 2012). "Accordingly, over-expression of ZEB2 and TWIST1 in surgical samples of both normal and tumor tissues can induce EMT, resulting in over-expression of representative EMT markers VIM, FN, and COLs and membrane signal transducers IL8, CXCL4, CCL5, CXCR4, PDGFRB, and TLR2." (PMID 21533028, 2011). "The tumor was positive for CD68 and vimentin in immunohistochemical staining." (PMID 22040611, 2011). "Vimentin was detected in the cytoplasm of tumour cells, non-malignant stroma and blood vessel endothelial cells." (PMID 22022619, 2011). "Vimentin and epithelial membrane antigen (EMA) were similarly expressed by tumor cells." (PMID 21320334, 2011). "Immunohistochemical analyses indicated that many of the tumor cells were positive for vimentin, while tumor cells were negative for cytokeratins, desmin, S-100 protein, actins, c-kit, and CD34." (PMID 21288322, 2011). "All tumor cells showed strong positive reactivity for vimentin and negative reactivity for CD31, CD34, and myoglobin." (PMID 21329505, 2011). "Immunohistochemically the tumor cells strongly expressed Vimentin, MyoD1, SMA and CD99, being negative for the remaining antibodies tested, including Myogenin and Desmin." (PMID 20701800, 2010). "The poorly differentiated tumor had reactivity for S100 protein and vimentin and was negative for epithelial and muscular markers stains, it was otherwise morphologically and clinically compatible with the diagnosis of SS." (PMID 29147174, 2010). "Immunohistochemically, the tumor cells were positive for vimentin and focally for CD68, but were negative for the other antibodies tested in vivo." (PMID 21092322, 2010). "There is no statistical significance between overexpression of vimentin with age, gender, tumor location, TNM stage and lymph node metastasis." (PMID 20701774, 2010). "Downregulation of E-cadherin in our system was correlated with changes in tumour cell morphology but not with changes of vimentin or α-smooth muscle actin expression (data not shown)." (PMID 20723242, 2010). "The mononuclear tumor cells (MTCs) showed immunoreactivity with vimentin, Ki-67 and p 53 and were negative for CD-68 expression." (PMID 20976205, 2010). "Basal tumors also lacked vimentin expression with the exception of the tumor-stromal interface (data not shown)." (PMID 20964822, 2010). "The unusual feature of the immunophenotype of the presented case is that, despite the epithelioid morphology, the tumour cells demonstrated only focal immuno-positivity to cytokeratins (CAM5.2) and, at the same time, strong positivity to mesenchymal markers (e.g. vimentin)." (PMID 19830109, 2009). "Vimentin expression was observed in 38 cases (21.2%), whereas 141 (78.8%) tumours were found to be vimentin-negative." (PMID 19695088, 2009). "Cells tumour was highly positive for vimentin and CD68 and negative for S100, CD34, Factor XIIIa and SMA." (PMID 20066060, 2009).
tumor (continued). "In the non-triple negative group, due to the limited number of vimentin-positive tumours, only not significant, although an obvious tendency towards such relationship was observed." (PMID 19695088, 2009). "Immunohistochemically, the tumor cells were diffusely and strongly positive for vimentin, but were negative for cytokeratin, smooth muscle actin, S-100 protein and neuron specific enolase." (PMID 19956483, 2009). "Tumor cells showed diffuse strong immunoreactivity for vimentin and patchy strong staining for CD10; no reactivities were found for AE1/AE3, desmin, S-100, LCA, CD20, c-kit, and CD31." (PMID 21151512, 2009). "Cells tumour was highly positive for vimentin and CD68 and negative for S100, factor XIIIa and CD34 and SMA." (PMID 20066060, 2009). "The angiogenic switch was presumably not accompanied by typical epithelial mesenchymal transition (EMT) at the tumor edges as we did not detect cells doubly positive for pro SP-C and vimentin or pro SP-C and N-cadherin." (PMID 19551151, 2009). "Vimentin-positive tumours affected younger women (p = 0.024), usually lacked estrogen and progesterone receptor (p < 0.001), more often expressed basal cytokeratins (<0.001), and were high-grade cancers (p < 0.001)." (PMID 19695088, 2009). "The primary tumor was 1.5 cm3 and although large, did not appear to invade the stroma and lacked vimentin expression." (PMID 18179684, 2008). "In contrast, vimentin expression in tumour epithelial cells was an independent negative prognostic indicator for DSS." (PMID 18854838, 2008). "Anti-vimentin immunostaining revealed positive vimentin immunoreactivity of the stroma and negative immunoreactivity of the tumor cells." (PMID 18179684, 2008). "Immunohistochemical analysis showed that the tumour cells expressed vimentin, but not smooth-muscle actin, CD34, or desmin." (PMID 18257933, 2008). "Immunohistochemical analysis showed that the tumour cells expressed vimentin, but not smooth-muscle actin (SMA), CD34, or desmin." (PMID 18257933, 2008). "High expression of vimentin was seen in 61% of poorly differentiated tumours, 39% of moderately differentiated tumours and no expression was seen in well-differentiated tumours." (PMID 18854838, 2008). "The tumor cells were simultaneously diffusely positive for epithelial markers i.e. the various cytokeratins CK, CK7, High molecular weight (HMWCK) and epithelial membrane antigen (EMA), along with a mesenchymal marker i.e. vimentin." (PMID 17324295, 2007). "On immunohistochemistry, the tumor cells were positive for smooth muscle actin (DAKO, Glostrup, Denmark), keratin MNF 116 (a pan-keratin with both high- and low molecular weight keratins from DAKO, Glostrup, Denmark) and vimentin (DAKO, Glostrup, Denmark)." (PMID 17250774, 2007). "The integrated intensity measurement of the antigenic isoform in each tumor type was directly compared to that of a neighboring non-antigenic vimentin isoform that is ubiquitously expressed in all tumor types examined." (PMID 18769604, 2006). "All neoplasms stained variably positive for CD 34, CD 99, BCL-2 and vimentin." (PMID 16824225, 2006). "Stain for cytokeratin is negative while tumor cells are positive for vimentin in clear cell sarcoma of the kidney." (PMID 16584570, 2006). "The tumor cells of GBM are immunoreactive for GFAP and Vimentin." (PMID 15967023, 2005). "Additionally, VIM was highly expressed in the densely fibrotic stroma of adenocarcinoma region, not in the tumor cells." (PMID 40873563, 2025). "Notably, STP tumor cells showed minimal vimentin expression, and were negative for smooth muscle marker (α-SMA) by IHC." (PMID 41044182, 2025).
tumor (continued). "Irrespective of the tumor type it appears LNs may process epithelial tumor cells in such a way that surface vimentin (EDV) is a recognized target." (PMID 40051499, 2025). "Stromal cells expressed the canonical mesenchymal stromal markers, including Vimentin, the CAF marker αSMA, and mesenchymal stem cell markers CD105 and CD73, across all culture conditions, reflecting the cellular phenotypes observed in the original tumor tissue." (PMID 40723172, 2025). "The cytoplasm of tumor cells was positive for vimentin and melanin A and negative for inhibin." (PMID 41451336, 2025). "In our case, the tumor was positive for vimentin and CD99 and negative for CK, NSE, and CD45." (PMID 40060231, 2025). "Furthermore, PADI4 knockdown resulted in an upregulation of E-cadherin and a downregulation of Vimentin (P<0.05), indicating that PADI4 depletion may inhibit the EMT process, further supporting its role in tumor progression and metastasis." (PMID 41208994, 2025). "The tumours were vimentin‐positive and negative for cytokeratin and smooth muscle actin." (PMID 40415599, 2025). "Vimentin and N‐cadherin are key markers of the epithelial–mesenchymal transition (EMT), a process that enhances cell motility and invasiveness, while MMP2 and MMP9 are matrix metalloproteinases involved in the degradation of the extracellular matrix, facilitating tumour invasion and metastasis." (PMID 40794013, 2025). "Next, we showed that hRAT-CMs increase the expression of mesenchymal markers, like desmin, N-cadherine and vimentin, in both tumor and non-tumor renal epithelial cells and that AT can stimulate the epithelial-mesenchymal transition (EMT) and therefore the metastatic capacity of cells." (PMID 40995093, 2025). "Furthermore, the IHC test indicated that administration of tRF‐34‐antagomir also suppressed the expression levels of Ki‐67, N‐cadherin, Vimentin, and CD34 protein levels and increased the expression levels of DAB2IP and E‐cadherin in the xenograft tumour tissues." (PMID 40263693, 2025). "Further Western blot analysis showed that RRM2 regulated the expression levels of MMP2, MMP9 and EMT-related proteins (N-Cadherin, Vimentin, Snail), suggesting that RRM2 may promote tumor cell invasion and metastasis by promoting matrix degradation and inducing epithelial mesenchymal transition." (PMID 41333212, 2025). "Moreover, the IHC results showed that the expression levels of Ki‐67, vimentin and CD206 were significantly lower and that the expression levels of E‐cadherin and CD86 were significantly greater in the tumor tissues of the sh‐MFGE8 migrasome group than in those of the sh‐NC migrasome group." (PMID 40056029, 2025). "For example, ovarian cancer-derived EVs upregulate CAF markers such as α-SMA, vimentin, desmin, and FSP-1 to facilitate normal fibroblasts to CAF-like transformation, thereby upregulating their motility, proliferation, invasiveness, and the pro-tumor crosstalk between tumor cells and CAFs." (PMID 40908470, 2025). "To establish the specificity of tumour production by C328S-VIM, we created another single substitution, Y117L, at the beginning of the rod domain and a double substitution containing C328S and Y117L in the same vimentin molecule (referred to as DMT in this article)." (PMID 40690373, 2025). "Importantly, vimentin expression in tumor cells significantly correlated with DFS (p = 0.016) but not with MFS or OS." (PMID 40647395, 2025). "Our study discerned that miR‐21‐related genes, such as ABCB1, SPRY1, ERGE, PIK3R1, SPTBN1, VIM, and others, which experienced downregulation in tumor sites, exhibited a negative correlation with tumor purity and a positive association with T cell infiltration, notably CD8+ T cells." (PMID 40567015, 2025). "Vimentin labeling was observed in all SCs within SCO tubules, regardless of tumor association." (PMID 40427255, 2025).
tumor (continued). "However, quantitative analysis of GATA6 and VIM expression in mouse tissue was deemed unfeasible due to the widespread expression of GATA6 in both non-malignant epithelial and tumor cells, and the intense stromal labelling of VIM." (PMID 41006303, 2025). "When the healthy and tumor groups were reorganized according to the patients’ age range (≤65 or >65 years old) and the patients’ gender (male or female), no statistically significant differential expression of CDH1 and VIM transcript levels were observed (p > 0.05)." (PMID 40305202, 2025). "Neither the histology, the thyroid-specific and oxidative gene expression profiles or the high percentages of vimentin-positive cells were impacted by Dicer1 inactivation, demonstrating that these changes are attributable to the presence of the tumor itself and not influenced by Dicer1 inactivation." (PMID 41002430, 2025). "The tumor cells were positive for vimentin but negative for CD10." (PMID 41000321, 2024). "Nesfatin-1 secreted by adipose tissue in the tumor microenvironment might directly influence tumor bone metastasis by regulating the expression and function of EMT-related proteins like E-cadherin, N-cadherin, and Vimentin." (PMID 38571500, 2024). "By contrast, there were strong negative correlations of E-cadherin with vimentin in all tumor regions (Pearson r =−0.81, r= −0.81 to −0.89; p < 0.001, p < 0.001), confirming its essential role as a key epithelial marker and concomitant downregulation during dysfunctioning EMT efforts." (PMID 39371729, 2024). "Tumor cells are usually positive for vimentin, but in a few cases, it is not expressed." (PMID 38989233, 2024). "The tumor tissues were then analyzed by Western blotting to detect the different expression levels of proliferation (Ki67 and PCNA), apoptosis (c-Casp3, c-PARP), metastasis (vimentin), related substrate (p-PDH, HDAC1), and cell cycle-related proteins (CDC25A, CDK4, CDK6, and Rb) in each group." (PMID 38948069, 2024). "Finally, both an Undefined (non-cellular artifact and/or population not defined by available biomarkers) and Tumor cell (Vimentin+) cluster were also classified during cellular phenotyping." (PMID 39333065, 2024). "C5AR1 knockdown effectively elevated E-cadherin expression and attenuated Vimentin expression in AGS, SGC7901 and MKN28 cells, indicating that aberrantly expressed C5AR1 might be involved in mediating the EMT phenotype of GC cells and even tumor metastasis." (PMID 38425243, 2024). "The animals were sacrificed, and the tumor tissue from stressed animals exhibited increased mRNA expression of the EMT-related genes Twist1, Twist2, Zeb1, Zeb2, Slug, and PLAGL2 and increased protein expression of PLAGL2, Ki67 (a proliferation marker), N-cadherin, and Vimentin." (PMID 38689092, 2024). "To determine whether IL-15 overexpression-mediated activation of the AKT-mTORC1 pathway is responsible for the upregulation of vimentin expression, we used LY294002 and rapamycin to inhibit AKT and mTORC1 activity, respectively, in cultured IL-15-overexpressing tumor cells." (PMID 38637902, 2024). "Immunohistochemically, CD34 and vimentin were positive while S100 was negative in tumor tissues." (PMID 39634408, 2024). "Compounds 3 and 4 significantly inhibited the invasion of HCT-116 cells and notably suppressed the expression of VEGFR-1 and vimentin (a biomarker of EMT), suggesting that they may inhibit tumor cell metastasis by preventing the EMT process through downregulation of VEGFR-1 expression." (PMID 38667800, 2024). "Also, in this stage, tumour cells show positive E-cadherin expression and negative vimentin expression." (PMID 38540190, 2024).